IFNA1 (interferon alpha 1)
Description:
Produced by macrophages, IFN-alpha have antiviral activities. Interferon stimulates the production of two enzymes: a protein kinase and an oligoadenylate synthetase.
Synonyms: LeIF D; IFNA@; IFL; IFN; IFN-ALPHA; IFNA13; IFN-alphaD
Tractability: Antibody: a drug acting on it is in phase 2 or 3 trials; its Gene Ontology location is reachable by antibodies, with high confidence; UniProt places it where antibodies can reach, with medium confidence; UniProt predicts a signal peptide or a membrane-spanning region.
Target class: Secreted protein
Gene: Protein-coding gene on chromosome 9 (21,440,439 to 21,441,316, forward strand). Ensembl gene ENSG00000197919.
Subcellular location: Secreted
Pathways (Reactome):
Immune System: Interferon alpha/beta signaling; Regulation of IFNA/IFNB signaling; TRAF6 mediated IRF7 activation
Disease: Evasion by RSV of host interferon responses; SARS-CoV-2 activates/modulates innate and adaptive immune responses
Hemostasis: Factors involved in megakaryocyte development and platelet production
Genetic constraint (gnomAD): Loss-of-function variants: 0 observed, 0.45 expected, observed/expected ratio (o/e) 0, 90% interval 0 to 1.84. That is too few expected variants to judge how well the gene tolerates losing a copy. Missense variants: 85 observed, 144.14 expected, observed/expected ratio (o/e) 0.59, 90% interval 0.49 to 0.71. Synonymous variants: 43 observed, 56.14 expected, observed/expected ratio (o/e) 0.77, 90% interval 0.6 to 0.99.
Homologues: Orthologues: macaque IFNA13 (95% identical), pig IFN-ALPHA-15 (67% identical), pig IFN-ALPHA-8 (67% identical), pig IFN-ALPHA-9 (67% identical), pig IFN-ALPHA-13 (66% identical), mouse Ifna9 (66% identical), pig IFNA1 (65% identical), mouse Ifna1 (64% identical), mouse Ifna13 (64% identical), mouse Ifna16 (64% identical), mouse Ifna6 (64% identical), pig IFN-ALPHA-4 (63% identical), and 31 more. Paralogues in human: IFNA13 (99% identical), IFNA6 (85% identical), IFNA5 (84% identical), IFNA14 (82% identical), IFNA2 (82% identical), IFNA21 (81% identical), IFNA4 (80% identical), IFNA10 (79% identical), IFNA17 (79% identical), IFNA8 (77% identical), IFNA16 (77% identical), IFNA7 (77% identical), and 4 more.
Diseases named in the same sentence as IFNA1 in open-access papers:
IFNA1 is named in the same sentence as 756 diseases in open-access papers, as found by Europe PMC text mining. Sharing a sentence is not in itself a finding about the gene and the disease. The quoted sentences say what the papers report.
viral infection (2,272 papers, 2002 to 2026). "The remaining 20 non-targetable SARS-CoV-associated disease genes include proteins (e.g., CD14, IFNA1, IFNB1, IL4, IL10, CCL5) having key roles in the immune-inflammatory response to viral infection as well." (PMID 33544720, 2021). "PUMA is a pro-apoptotic member of the Bcl-2 protein family, whereas IFNα1 and IFNβ1belong to type I interferons that are involved in the innate immune response in humans against viral infections." (PMID 21625585, 2011). "It exhibits unique features that have evolved to adapt to virus infections, such as lower NLRP3 production, greater expression of IFNα1, and greater phosphorylation of IRF3." (PMID 40108733, 2025). "To better understand the response of microglia after virus infection, we investigated the IFNB1, IFNA1, and IFNA5 expression at the MOIs 0.1, 0.01, and 0.001, where the viability was near 50% after infections at 3 DPI." (PMID 38213031, 2024). "We found no expression of IFNA1 and IFNA5 (data not shown), and dose-dependent IFNB1 expression after virus infection, indicating innate immune signaling activation." (PMID 38213031, 2024). "The mRNA of Ifna1, 2, 5, 7, 9 and 11 was found in the spinal cord during TMEV-IDD using a DNA microarray but the expression of these genes was also not induced by virus infection." (PMID 36872323, 2023).
COVID-19 (729 papers, 2020 to 2026). A disease caused by infection with severe acute respiratory syndrome coronavirus 2. "This retrospective cohort study demonstrated that arbidol and interferon alpha-1b contribute to reducing the risk of developing severity in moderate COVID-19 patients." (PMID 34238341, 2021). "Different major dysregulated biosignatures including but not limited to Interferon Alpha 1 (IFNA1), Interferon Alpha Inducible Protein 6 (IFI6), Toll-Like Receptor 4 (TLR4) and interleukin-6 (IL6) are linked to host responses to COVID-19." (PMID 39040605, 2024). "Therefore, this unexpected reciprocal correlation of IFNA1 and IL12p40, mainly expressed in macrophages, might also be strongly associated with the heterogeneity of dysregulated inflammation in pneumonic COVID-19 patients." (PMID 36776879, 2023). "Our data supports the role for interferons in COVID-19 as patients who died had 2.5-fold increase in expression of interferon 1 alpha (IFNA1)." (PMID 36130991, 2022). "Antiviral drugs including arbidol, interferon alpha-1b, lopinavir–ritonavir and ribavirin were used to treat COVID-19 patients." (PMID 34238341, 2021). "Nonetheless, enhanced IFNA1 and a suppressed IL12p40 response strongly associated with persistent and overt inflammatory responses were detected even in a proportion of moderate pneumonia patients (8.3%, MG2) and in more than half (59.4%, SG2) of severe COVID-19 patients." (PMID 36776879, 2023). "Activation of ISGs appear to be beneficial in controlling SARS-CoV-2, but over-activation of proinflammatory cytokines and downregulation of certain ISGs (IFNA1, APOBEC3G, and FADD) and microRNAs (miR-155 and miR-130a) may be associated with progression to severe/critical COVID-19." (PMID 33780352, 2021). "IFNA1 also presented a robust positive correlation with CCL11, FASLG, and IL23A in severe patients, and their correlation power was gradually enhanced as COVID-19 severity increased." (PMID 36776879, 2023). "When comparing COVID-19 mild vs critical patients, we identified IFNLR1, IFNA1, CXCL9, CXCL10, IL15 and IL15RA to be upregulated in mild patients." (PMID 33473155, 2021). "This exercise revealed that, whereas the DS IFN score tracks preferentially with IFNG and IFNL1 in DS, this same ISG signature correlates significantly with eight different IFNs in COVID-19, five of which are type I IFNs (i.e., IFNA2, IFNA7/17/21, IFNA1, IFNA4/16, and IFNA10)." (PMID 37379383, 2023). "In addition, IL12p40 was the top negative correlate of IFNA1 in the severe group, and their inverse correlation was gradually enhanced according to COVID-19 severity." (PMID 36776879, 2023). "An elevated IFNA1 response displayed a strong negative correlation with IL12p40 and CX3CL1, whereas it presented a robust positive correlation with CCL11, FASLG, and IL23A, especially in severe COVID-19 patients." (PMID 36776879, 2023). "This included IFNα1 and IFNβ1 (respectively), IFN-II, such as IFNγ (respectively), and IFN-III, except for IFNλ1, which was expressed in COVID-derived PBMCs from critical COVID-19 patients, but not in COVID-derived monocytes." (PMID 37310504, 2023).
systemic lupus erythematosus (521 papers, 2005 to 2026). An autoimmune multi-organ disease typically associated with vasculopathy and autoantibody production. "A previous work has discovered that chromosome 1q32 locus linked to the risk of systemic lupus erythematosus (SLE) and miR-181b located on the susceptibility site with downregulation inversely correlating to its target molecular interferon alpha 1 (IFNA1)." (PMID 32382553, 2020). "The importance of interferons was highlighted in our previous results on the TLR4 signaling pathway, where TLR4, TICAM1, TICAM2, TBK1, IRF3, IFNA1, and IFNA2 mRNAs showed changes in the murine lupus-like models." (PMID 29349090, 2017). "This revealed that three prioritised lupus genes (USP18, STAT1, IFNA1-17) were shared with the 13 category I genes (IFNAR1/2 signal transduction proteins) and four prioritised genes (IRF1/5/8 and OAS1) were shared with the 38 category II genes (transcriptional targets of interferon response)." (PMID 41038828, 2025).
influenza (266 papers, 2008 to 2026). An acute viral infection of the respiratory tract, occurring in isolated cases, in epidemics, or in pandemics; it is caused by serologically different strains of viruses (influenzaviruses) designated A, B, and C, has a 3-day incubation period, and usually lasts for 3 to 10 days. "Noteworthy, syncytin-1 has been shown to weaken the antiviral response against Influenza, leading to reduced production of IFNA1, IFNL1, and IFN-γ and inducing IL10 release by peripheral monocytes (PBMCs)." (PMID 39273061, 2024). "Among the 28 vaccines, most subunit vaccines and all viral vaccines, including three Influenza vaccines (Fluarix, Fluzone, and Vaxigrip), are not directly associated with IFNG; however, they are frequently associated with IFNA1 (IFN-alpha 1)." (PMID 21624163, 2011).
Autoimmunity (173 papers, 2005 to 2026). The occurrence of an immune reaction against the organism's own cells or tissues. "Our discovery of IFN-α1 AS RNA as a regulator of the IFNA1 gene at the mRNA level raises the possibility that dysfunction of the AS RNA could contribute to autoimmunity by failure to sustain IFNA1 gene expression and function." (PMID 23224365, 2013). "Intriguingly, we found that BaP exposure of MRL mice results in the upregulation of serum IFNg but not IFNa1/a2, which is similar to the reported scenario of mercury-induced autoimmunity." (PMID 41155532, 2025).
HIV-1 infection (135 papers, 2008 to 2026). The type species of lentivirus and the etiologic agent of acquired immunodeficiency syndrome (AIDS). "Thus, the induction of weakly antiviral subtypes such as IFNα1 by pDCs during acute HIV-1 infection may have important consequences for early HIV-1 evolution." (PMID 26529416, 2015).
chronic hepatitis C (116 papers, 2005 to 2025). "To better understand the dynamics between type I and III IFNs expression in chronic hepatitis C patients, we also quantified the expression of IFNA1, IFNL1, IFNL2, IFNL3 and IFNL4 in 24 healthy volunteers." (PMID 34307188, 2021).
breast cancer (109 papers, 1993 to 2026). A primary or metastatic malignant neoplasm involving the breast. "It has showed that Ifna1 was endowed with marked antiangiogenic activity in breast cancer and ovarian cancer models, and considered as a suitable candidate gene for this therapeutic approach." (PMID 19397828, 2009).
liver disease (50 papers, 2009 to 2025). "Further, interferon-alpha encoded by IFNA1 can inhibit the replication of the HBV, thereby leading to the remission of liver diseases." (PMID 31565062, 2019).
AIDS (46 papers, 2005 to 2025). A syndrome resulting from the acquired deficiency of cellular immunity caused by the human immunodeficiency virus (HIV). "Additionally, patients with Acquired Immunodeficiency Syndrome (AIDS; stage C) showed significantly higher expression of IFNA1/13, IFNA8, IFNA14, IFNA16, IFNA17, and IFNA21 mRNA." (PMID 38543729, 2024).
glioma (45 papers, 2007 to 2025). A benign or malignant brain and spinal cord tumor that arises from glial cells (astrocytes, oligodendrocytes, ependymal cells). "As compared to the normal brain tissues, the genes with decreased copy numbers, such as IFNA1, IFNB1, and IFNG, had lower expression levels in glioma." (PMID 36428756, 2022).
HCMV infection (45 papers, 2007 to 2026). "In the context of UL88-STOP-mCh HCMV infection, we also observed upregulation of the Type I interferons IFN-β and IFN-α2, although IFNα1, IFNα4, and IRF3 were similarly expressed after infection with TB40/E-mCh or UL88-STOP-mCh HCMV." (PMID 40638072, 2025).
lymphoma (41 papers, 2002 to 2025). A malignant (clonal) proliferation of B- lymphocytes or T- lymphocytes which involves the lymph nodes, bone marrow and/or extranodal sites. "In addition, we observed co-expression of immune mediators, such as interferons and their targets (IFNA1-2, IFNA7-8, IFNB1, and IFNG), as well as proinflammatory cytokines (IL-1B and IL12B) and chemokines and their receptors (CXCL9-11 and CXCR3) by CpG(B)-STAT3dODN-treated lymphoma cells (right)." (PMID 29433938, 2018).
type 1 diabetes (39 papers, 2005 to 2026). "IFNA1 expression was increased by 75% (p = 1.30 × 10−3, 95% CI −0.44, −0.09) and IFNA10 expression was increased by 136% (p < 1.00 × 10−4, 95% CI −0.50, −0.18) in individuals with new-onset type 1 diabetes." (PMID 33973017, 2021).
pneumonia (35 papers, 2013 to 2026). An acute, acute and chronic, or chronic inflammation focally or diffusely affecting the lung parenchyma, caused by an infection in one or both of the lungs (by bacteria, viruses, fungi, or mycoplasma.). "We observed elevated IFNA1 and suppressed IL12p40, presenting a robust inverse correlation in severe patients, which was strongly associated with persistent hyperinflammation in 8.3% of moderate pneumonia patients and 59.4% of severe patients." (PMID 36776879, 2023).
Arthritis (32 papers, 2006 to 2026). Inflammation of a joint. "Surprisingly, certain genes implicated in arthritis pathogenesis were more than 2-fold higher in arthritic V-KO joints, including NOS2, IL-23a, and IFNA1." (PMID 29216931, 2017).
colitis (22 papers, 2011 to 2025). Inflammation of the colon. "Second, many genes differentially expressed between TWD and AIN diets at colitis were still upregulated at the recovery time point compared to pre-DSS, though not markedly more so in TWD-fed mice (e.g., Ifna1, Il6, Tnf)." (PMID 32093192, 2020).
gastric cancer (21 papers, 2013 to 2025). A primary or metastatic malignant neoplasm involving the stomach. "MTMR2 an essential promoter in gastric cancer invasion and metastasis by inactivating IFNA1/STAT1 signalling and acts as a new prognostic indicator and a potential therapeutic target for gastric cancer." (PMID 35057823, 2022).
parasitemia (19 papers, 2011 to 2026). "Both IFN treatments reduced parasite burden in the brain and decreased infiltrating CD8+ T cells in the brain compared to control mice, but only IFNα1/α8 treatment decreased blood parasitemia." (PMID 33408718, 2020).
Down syndrome (15 papers, 2010 to 2026). "With the exception of IFNA1 expression, type I interferons (IFNA2 and IFNB1) were all upregulated, indicating that the axis IFNAR-STAT-OAS is upregulated in Down syndrome." (PMID 33479353, 2021).
neuroblastoma (13 papers, 2012 to 2024). Neuroblastoma (NB) is the most common solid, extracranial childhood tumor. "We also observed that neuroblastoma cells exposed to EVs from QKI-depleted HeLa cells expressed significantly more IFNA1 and IL1B mRNA than did neuroblastoma cells exposed to EVs from control shRNA-treated cells." (PMID 39308343, 2024).
head and neck cancer (6 papers, 2004 to 2022). A primary or metastatic malignant neoplasm affecting the head and neck. "Interferon alpha 1 (IFNA1) could encode a member of the type I interferon, and expression of IFNA1 is associated with HPV-positive head and neck cancers." (PMID 36120433, 2022).
endometrial cancer (5 papers, 2016 to 2025). Primary or metastatic malignant neoplasm involving the endometrium (mucous membrane that lines the endometrial cavity). "CD4, EPO, SOS1 and IFNA1 are related to several cellular mechanisms such as hematopoietic cell lineage determination, gonadotropin-releasing hormone (GnRH) signaling, cytokine-cytokine receptor interactions and endometrial cancer." (PMID 27832168, 2016).
leishmaniasis (5 papers, 2018 to 2026). Infectious disease that is transmitted through the bite of hematophagous female phlebotomine sand flies. "Furthermore, expression of IFNA1 and IFNB1 was highest in CD1c+ DCs relative to B cells (CD19+) and monocytes (CD14+), other likely cellular sources of these cytokines in experimental leishmaniasis." (PMID 32101732, 2020).
alcoholic liver diseases (2 papers, 2015 to 2024). A disorder caused by damage to the liver parenchyma due to alcohol consumption. "Among the top 30 genes in the gene regulatory network, 7 genes are enriched in alcoholic liver disease (hsa04936), including TNF, IL6, IFNA1, CYP2E1, ALDH2, ADH1B, ADH1C." (PMID 38429802, 2024).
papillary thyroid cancer (2 papers, 2019 to 2022). "Our analysis concludes that TIMP1, LOX, CD276, IFNA1, TLR2, and POSTN are identified as thyroid cancer biomarkers, which lead to the different clinical courses of a woman older than 55 years old with papillary thyroid cancer." (PMID 36120433, 2022). "According to the ROC results, TIMP1, LOX, CD276, IFNA1, TLR2, and POSTN were considered to play a more critical role in malignant papillary thyroid cancer or immature cancer of papillary thyroid cancer." (PMID 36120433, 2022). "TIMP1, LOX, CD276, IFNA1, TLR2, and POSTN have different expressions in PTCs, which lead to the various clinical courses of a woman older than 55 years old with papillary thyroid cancer." (PMID 36120433, 2022).
thyroid cancer (2 papers, 2022 to 2025). "Interferon alpha 1 could be found in normal thyroid cells and differentiated thyroid cancer and also used in some diseases, but long-term interferon (IFN) therapy is frequently associated with side effects on the thyroid gland." (PMID 36120433, 2022). "Especially CD276, POSTN, and IFNA1 may be considered as new potential biomarkers associated with the prognosis of thyroid cancer." (PMID 36120433, 2022). "Especially CD276, POSTN, and IFNA1 may be considered as new biomarkers associated with the prognosis of thyroid cancer." (PMID 36120433, 2022).
intrahepatic cholangiocarcinoma (1 paper, 2024). A carcinoma that arises from the intrahepatic bile duct epithelium in any site of the intrahepatic biliary tree. "Conversely, a modest increase in the expression of IFNA1, IFNB1, and IRF1 was observed in liver tissue sections from patients with intrahepatic cholangiocarcinoma." (PMID 38817870, 2024).
tuberculoid leprosy (1 paper, 2014). A principal or polar form of leprosy in which the skin lesions are few and are sharply demarcated. "Of the 24 soluble mediators of inflammation that were measured, 7 showed significant differences between lepromatous and tuberculoid leprosy (CCL2, CCL17, CCL18, IFNA1, IL10, IL22, and TNF)." (PMID 25412496, 2014).